ELN (elastin)
Description:
Major structural protein of tissues such as aorta and nuchal ligament, which must expand rapidly and recover completely. Molecular determinant of the late arterial morphogenesis, stabilizing arterial structure by regulating proliferation and organization of vascular smooth muscle (By similarity).
Synonyms: WBS; WS; SVAS; ADCL1
Tractability: Antibody: UniProt places it where antibodies can reach, with high confidence; its Gene Ontology location is reachable by antibodies, with high confidence; UniProt predicts a signal peptide or a membrane-spanning region; the Human Protein Atlas places it where antibodies can reach. Other modalities: a drug acting on it is in phase 2 or 3 trials.
Target class: Structural protein
Gene: Protein-coding gene on chromosome 7 (74,027,789 to 74,069,909, forward strand). Ensembl gene ENSG00000049540.
Subcellular location: Secreted, extracellular space, extracellular matrix
Subcellular location (Human Protein Atlas): Plasma membrane; Predicted to be secreted
Pathways (Reactome):
Extracellular matrix organization: Degradation of the extracellular matrix; Elastic fibre formation; Molecules associated with elastic fibres
Gene Ontology:
Molecular function: protein binding; extracellular matrix constituent conferring elasticity; extracellular matrix structural constituent; extracellular matrix binding
Biological process: outflow tract morphogenesis; animal organ morphogenesis; aortic valve morphogenesis; blood circulation; extracellular matrix assembly; regulation of smooth muscle cell proliferation; respiratory gaseous exchange by respiratory system
Cellular component: elastic fiber; extracellular matrix; extracellular region; non-collagenous component of interstitial matrix
Genetic constraint (gnomAD): Loss-of-function variants: 60 observed, 106.83 expected, observed/expected ratio (o/e) 0.56, 90% interval 0.46 to 0.7. The upper end of that interval is the gene's LOEUF score, 0.7, which puts it in group 2 of 6, group 1 being the genes least tolerant of losing a copy. Missense variants: 805 observed, 908.88 expected, observed/expected ratio (o/e) 0.89, 90% interval 0.83 to 0.94. Synonymous variants: 331 observed, 362.15 expected, observed/expected ratio (o/e) 0.91, 90% interval 0.83 to 1.
Gene-disease validity (ClinGen):
ClinGen rates the evidence that ELN causes each of these diseases.
cutis laxa, autosomal dominant 1 (autosomal dominant): Definitive. Any autosomal dominant cutis laxa in which the cause of the disease is a mutation in the ELN gene.
Homologues: Orthologues: chimpanzee ELN (99% identical), macaque ELN (94% identical), dog ELN (77% identical), pig ELN (77% identical), mouse Eln (77% identical), rat Eln (75% identical), tropical clawed frog eln1 (51% identical).
Diseases named in the same sentence as ELN in open-access papers:
ELN is named in the same sentence as 418 diseases in open-access papers, as found by Europe PMC text mining. Sharing a sentence is not in itself a finding about the gene and the disease. The quoted sentences say what the papers report.
aneurysm (168 papers, 2011 to 2025). Bulging or ballooning in an area of an artery secondary to arterial wall weakening. "Loss of elastin represents an early event in aneurysm formation, while collagen degradation is a critical factor contributing to rupture." (PMID 41323733, 2025). "The loss of elastic fibers is a key feature of aneurysm development, with elastin content continuously decreasing during aneurysm growth." (PMID 41280888, 2025). "A large-scale retrospective study in China reported that two single-nucleotide polymorphisms in the elastin gene are associated with the development and rupture of IAs, further emphasizing the role of elastin in aneurysm rupture." (PMID 40244203, 2025). "Histologically, both aneurysms and dissections are associated with the degeneration or destruction of EFs/EL, conditions collectively known as elastin-associated arteriopathy." (PMID 40001457, 2025). "CCR2+ macrophage tissue infiltration was associated with overall aneurysm deterioration, such as severe elastin degradation and increased MMP9 24 and MMP2 25 activity when compared to controls." (PMID 40365294, 2025). "The reduced elastin production, fragmented EFs/EL, and loss of elastin are closely associated with several arterial diseases, including hypertension, atherosclerosis, and arteriopathy, such as aneurysms or dissections." (PMID 40001457, 2025). "Collectively, these advances underscore the pivotal roles of elastin not only as a structural determinant of aneurysm development but also as a diagnostic and therapeutic target." (PMID 41148811, 2025). "It is well established that MFS aneurysm is associated with aortic wall weakening and the fragmentation of elastin fibers within the aortic wall." (PMID 39684412, 2024). "As ascending aorta dilate, the aneurysms exhibited significantly increased energy loss, which is related to aortic size and elastin and collagen composition imbalance." (PMID 37193023, 2023). "The substantial loss of elastin content, accompanied by the fragmentation of elastic laminae and fibers, is a well-documented feature of aneurysms, a pathological condition marked by stiffened and dilated arterial walls." (PMID 38132820, 2023). "Degradation of most of the elastin of the bifurcation apex wall at the age 40–70 years will lead to elasticity loss, bulge out of the arterial wall, and ultimately formation of an aneurysm at the bifurcation." (PMID 38129685, 2023). "Historically, BAV-related aneurysm pathogenesis had been attributed to the destruction of collagen and elastin in media and adventitia, and loss of SMCs with thinning of aortic wall." (PMID 34648622, 2022). "In BAV disease, abnormal flow patterns with elevated wall shear stress associate with aneurysm progression and focal elastin degeneration." (PMID 35224059, 2022). "Other proteins include fibronectin, which alters the elastic modulus and mean stress of the vessel wall, and fibulin, which interacts with ECM proteins, such as elastin, and its shortage causes several problems including an aneurysm, rupture, and hemorrhage." (PMID 36138491, 2022). "Enlarged rAML is at a high risk of rupture due to abnormal elastin-poor tortuous vessels predisposed to aneurysm formation causing WS, and heterogeneous proportion is often altered on CT by hemorrhage within the lesion and perirenal hemorrhage." (PMID 34485374, 2021). "Consistent with these latter observations, genetic or pharmacological inactivation of lysyl oxidases, enzymes necessary for collagen and elastin cross-linking, cause or exacerbate aneurysm in patients and animal models." (PMID 33514025, 2021). "Dysregulated or defective elastin biosynthesis in both human genetic disorders (eg, Williams syndrome) and in elastin-deficient mice is also accompanied by aneurysms and occlusive lesions, similar to patients with TSC." (PMID 34617060, 2021).
aneurysm (continued). "Loss of elastin and the increased deposition and crosslinking of collagen during aneurysm development translate into biomechanical changes that include reduced distensibility and increased stiffness of the aorta." (PMID 33514025, 2021). "Accordingly, fibulin-4 deficiency results in disorganized collagen and elastin fibers in the aortic wall as well as aneurysms of the ascending aorta in both patients and mouse models." (PMID 33514025, 2021). "Two of the aneurysm specimens we examined were low outliers for cross-sectional elastin consistent with marked loss of elastic fibers; the patients’ co-morbidities were unremarkable and without a family history of aortic aneurysms." (PMID 34162971, 2021). "Energy loss has been reported to increase with aneurysm size and to strongly correlate with histological changes in thoracic aortic aneurysms, such as advanced medial degeneration, and greater collagen-to-elastin ratios." (PMID 33659281, 2021). "Since the positions of disturbed blood flow region have been correlated with the development of atherosclerotic and aneurysms and associated with alteration of elastin and collagens, we evaluated the effects of flow on ECM formation and composition." (PMID 32596117, 2020). "The striking difference in the aneurysm groups was in the inner (innermost medial region) and outer regions (adventitial region) of the wall, with a localized loss of elastin most pronounced in DA." (PMID 31679706, 2020). "Collagen defects can lead to aneurysm rupture, while elastin depletions are associated with continuous dilation." (PMID 33613530, 2020). "Several key changes in the arterial wall occur that are thought to lead to aneurysm formation, including loss of elastin content in the internal elastic lamina and reduction of the tunica media leading to weakening of the wall." (PMID 31428158, 2019). "As these MMPs are implicated in aneurysm formation through elastin degradation, their opposing trends provide further evidence for antagonistic phenotype activation." (PMID 31428158, 2019). "In some studies, loss of elastin and collagen of the aortic wall has been demonstrated to induce the development of aneurysms." (PMID 27701487, 2017). "Loss of elastin has long been considered the hallmark of aneurysm formation, but it is now accepted that impaired collagen homeostasis is the main cause." (PMID 27527829, 2016). "Increased matrix metalloproteinase (MMP) activity has been implicated in aneurysm formation through elastin destruction and collagen degradation." (PMID 23460850, 2013). "Due to the high affinity of calcium for elastin, calcium deposition within the elastic network of the media can cause the calcium–elastic tissue complex to weaken the vessel wall and develop aneurysm." (PMID 23844207, 2013). "Specifically MMP-2 and MMP-9 have been implicated in the pathogenesis of aneurysm due to their capability to degrade elastin and increased expression levels in the aneurysm tissue and the plasma of patients." (PMID 22187650, 2012). "Additionally, elastin fragmentation increases the susceptibility of arteries to pressure-induced damage, increasing the risk of aneurysm formation, particularly in the abdominal aorta." (PMID 39898976, 2025). "Elastin expression is well established as a particularly key contributing factor to the mechanical behavior of blood vessels, and it thus remains crucial to understanding development and clinical outcomes associated with incidental aneurysm findings." (PMID 40566064, 2025). "Biomechanical models and hemodynamic studies suggest that regions of post-stenotic dilation are prone to wall stress concentrations, which can predispose to both aneurysm formation, via elastin degradation and medial thinning, and to dissection through intimal tear propagation." (PMID 40717878, 2025).
aneurysm (continued). "In human AAA specimens, reduced elastin content, impaired cross-linking, and extensive fiber fragmentation are consistently observed, while experimental studies across multiple animal models confirm that elastin degradation directly correlates with aneurysm initiation, expansion, and rupture risk." (PMID 41148811, 2025). "Contradictory to its profibrotic role in fibroblasts, CCN2 deficiency in SMC results in reduced elastin mRNA but increased breakage in aneurysm tissue that could compromise the overall strength of the vascular wall." (PMID 36625347, 2023). "The elastin may provide great support for the integrity of the arterial wall, and degradation and deficiency of this material will cause arterial injury and aneurysm presence." (PMID 38129685, 2023). "The matrix glycoprotein fibulin-4 functions as an enhancer of lysyl oxidase activity and as a recruiter of immature elastin molecules: when mutated, the disruption of the elastic fibers and collagens on the aortic wall drives the aneurysm formation, as shown in both human and mouse models." (PMID 35892496, 2022). "Since these AAA formed by elastase administration which causes severe elastin degradation in all mice, we had hypothesized that both male and female mice would form similar large aneurysms." (PMID 34997075, 2022). "The authors suggested that the reduction of collagen and elastin in aorta of hypertensive patients with AA compared with their normotensive counterparts may explain the larger size of aneurysms and predispose to eventual rupture." (PMID 33006035, 2021). "However, the loss of elastin and collagen fibers in ruptured aneurysms are in line with the loss of elasticity and repair mechanism of the vessel wall during disease progression." (PMID 32704100, 2020). "Since the size of aneurysms correlates with vessel wall damage, and therefore increases the risk of rupture, we performed Verhoeff-Van Gieson staining of the control and diseased tissues to detect elastin fiber alterations." (PMID 31035427, 2019). "Furthermore, increased elastin content associated with miR-181b inhibition was accompanied by a more stable composition of atherosclerotic plaques and aneurysms, including greater collagen accumulation and enhanced smooth muscle cell to macrophage ratio." (PMID 27756793, 2017). "We next investigated whether Nec-1 protects mice from developing key pathological features of aneurysms, including disruption of elastin fibers, the loss of aortic SMCs and infiltration of imflammatory cells." (PMID 28186202, 2017). "The imbalance of excessive elastin degradation is the main cause of aneurysms." (PMID 25243605, 2014). "Typical histological features of SAM are the following: outer layer of media predominantly affected, alternating stenoses and aneurysms with disruption of elastin." (PMID 40951101, 2025). "MMPs are enzymes that degrade ECM components, such as collagen and elastin in the abdominal aortic wall, driving arterial wall remodeling and progressive dilation, ultimately leading to aneurysm formation." (PMID 40643529, 2025). "It is assumed that rupture involves more significant elastin degradation and consequently a greater increase in desmosine levels compared to stable aneurysms." (PMID 40142864, 2025). "A hallmark pathological feature of AAA tissue is the fragmentation of elastic fibers and the depletion of elastin, a process that typically arises during the early stages of aneurysm expansion and continues up to rupture." (PMID 41323733, 2025). "Our results confirm that GroEL aggravates elastin fragmentation and collagen disorganization, consistent with enhanced aneurysm formation." (PMID 40869102, 2025). "Similar to the localized treatments, IV delivered MSCs appeared to attenuate aneurysm expansion, and protect against elastin degradation." (PMID 41323882, 2025).
aneurysm (continued). "Consistent with this logic, a growing body of preclinical work has introduced elastin-centric therapies that show promising effects on aneurysm growth, wall composition, and inflammatory tone." (PMID 41148811, 2025). "The results showed that the AAA mice with an administration of live A. muciniphila exhibited reduced plasma FITC fluorescence intensity, systemic LPS levels, aneurysm diameter, and elastin degradation." (PMID 40299521, 2025). "In the treatment of aortic aneurysms, these nanoparticles deliver elastin-stimulating agents to the aneurysm site, promoting the regeneration of elastin fibers and restoring structural integrity to the vessel wall." (PMID 39595942, 2024). "The progressive disease state is further exacerbated by the activity of elastase, which precipitates elastin for degradation and aneurysm formation." (PMID 39742024, 2024). "In conclusion, this review has highlighted the promising role of nanoparticles in the treatment of aneurysms, particularly in targeting elastin degradation, SMC dysfunction, and inflammation." (PMID 39595942, 2024). "Research has also shown that XIST in thoracic aortic aneurysm (TAA) acts as a “sponge” to absorb miR-29b-3p, leading to overexpression of elastin (Eln) in VSMCs and promoting smooth muscle cell apoptosis, indicating its role in aneurysm development." (PMID 38895538, 2024). "Overall, elastin appears to play a key role in arterial elongation and aneurysm development, and both conditions have the potential to contribute to the formation of the other." (PMID 39598238, 2024). "Fibrillin functions as a scaffold for elastin, is an important regulator for bioavailability of active TGF-β, and mutations in fibrillin are a well-known cause for aneurysms in Marfan syndrome." (PMID 38636100, 2024). "The progressive disease state is further exacerbated by the activity of elastase, which precipitates elastin degradation and aneurysm formation." (PMID 39742024, 2024). "The genetic deletion of MMP-12 resulted in a reduced elastin degradation and aneurysm severity, culminating in protection from aneurysm rupture and related sudden death." (PMID 38891996, 2024). "On histologic analysis, percent area of elastin was significantly greater in normal controls compared with aneurysms of the ascending aorta (P < .001)." (PMID 38204645, 2023). "Specifically, elastin degradation occurs during aneurysm progression, releasing elastin-derived peptides into the circulation." (PMID 37799778, 2023). "In summary, alterations in the structure of elastin and collagen contributes towards aneurysm formation and progression." (PMID 37799778, 2023). "Consistently, as one of the dihydropyridine calcium channel blocker, amlodipine has been demonstrated to significantly promote elastin degradation and enhance matrix metalloproteinase-9 activity in experimental porcine aneurysm." (PMID 37383707, 2023). "It has previously been shown that serum levels of A1AT are higher in AAA patients than those with aortic-occlusive disease, highlighting the role of elastin degradation during aneurysm progression and the response to alleviate increased elastase activity." (PMID 37799778, 2023). "Changes in PG expression associated with maintaining ECM homeostasis within the aortic wall have been identified that favour aneurysm or dissection formation through distorting elastin and collagen arrangements or altering proteolysis of ECM components." (PMID 36012466, 2022). "Elastin degradation is one of the hallmarks of aneurysm formation, we next examined integrity of elastin layers 4 weeks after Ang II administration." (PMID 35414069, 2022). "Degradation or disorganization of elastin and collagen fibers therefore compromises arterial structure and function and has been shown to play an important role in aneurysm formation." (PMID 35492343, 2022).